BNIP3 (BCL2 interacting protein 3)
Diseases named in the same sentence as BNIP3 in open-access papers (continued):
Sharing a sentence is not in itself a finding about the gene and the disease.
tumor (continued). "For example, in glioblastoma tumor cells, despite the fact that BNIP3 levels were elevated in the hypoxic areas of the tumors, its localization was not mitochondrial or cytoplasmic as expected, but nuclear." (PMID 30250843, 2018). "The hypoxia responsive protein BNIP3, plays an important role in promoting cell death and/or autophagy, ultimately resulting in a cancer type-dependent, tumour-enhancer or tumour-suppressor activity." (PMID 29707136, 2018). "BNIP3 upregulation is known to induce prosurvival patterns and tumor aggressiveness in several cancers." (PMID 29207653, 2017). "Fibroblasts with a high expression of BNIP3 accelerated tumor growth, while overexpression of ATG16L1 showed constitutive activation of autophagy and increased tumor growth." (PMID 28930154, 2017). "BNIP3-dependent mitophagy is required to limit mitochondrial mass and ROS levels in growing tumors; its loss leads to HIF-1α-dependent increases in tumor growth and increased progression to metastasis." (PMID 28932704, 2017). "The downregulation of the BNIP3 gene has been associated with chemo-resistance in vivo and in our study the BNIP3 gene was upregulated in a tumour model that mimics an in vivo situation." (PMID 28509858, 2017). "Significant differences were noted between BNIP3 expression and the parameters tumor stage, N stage and clinical stage." (PMID 28968982, 2017). "BNIP3 is a pro-apoptotic member of the Bcl-2 family induced by hypoxia in anoxic regions of tumours and is antagonistic to pro-survival proteins like Bcl-2 and Bcl-xl." (PMID 28144288, 2017). "Immunohistochemistry analysis revealed higher BNIP3 expression in the wt-CL1-5 tumours than in BafA1-treated-CL1-5 tumours or normal mouse lung, confirming that cell lines with low AhR continue to exhibit high expression of autophagy-related proteins in vivo." (PMID 28195146, 2017). "Protein levels of VEGF and BNIP3 that are HIF-1-controlled pro-survival target genes were inversely correlated to tumor ascorbate content." (PMID 29084538, 2017). "Our results suggest that the downregulation of BNIP3 in TNBC cells significantly increased the anti-tumor effects of IR and YCW1 through the induction of autophagic cell death." (PMID 27286975, 2016). "TGF-β1 pro-treatment in Star-treated NIH3T3 fibroblasts significantly enhanced the expression of BNIP3, Beclin 1 and LC3β-II/I conversion in the mixed xenograft tumor, while 3-MA suppressed the effects of TGF-β1." (PMID 26716641, 2016). "Notwithstanding a modest (20-30%) reduction in the mRNA levels of HIF-1α and its downstream target genes VEGF and BNIP3, we observed significant differences in tumor growth between silenced DTC and control cells." (PMID 27105499, 2016). "The knockdown of BNIP3 was shown to inhibit autophagy and promote the necrotic cell death of tumour cells." (PMID 27628424, 2016). "High Bnip3 is reported to correlate with invasive tumor behavior in breast and colorectal cancers, and poor prognosis in non-small cell lung, prostate and endometrial cancers." (PMID 26611876, 2016). "The combined anti-tumor effects of YCW1 and IR were also observed in an orthotopic mouse model; combination therapy resulted in a significant increase in autophagy and decreased tumor tissue expression of BNIP3 in the tumor tissue." (PMID 27286975, 2016). "The authors report that deleting Bnip3 promoted tumor growth and malignancy, and resulted in the accumulation of dysfunctional, ROS-producing mitochondria." (PMID 26611876, 2016). "The adverse tumor-promoting effects of chronic mitophagy inhibition arising from deletion or inactivation of genes such as Parkin and BNip3, particularly induction of the Warburg effect, argue against targeting mitophagy as a therapeutic strategy." (PMID 25810907, 2015). "Loss of Parkin, as already mentioned, promotes the Warburg Effect, tumorigenesis in the liver, and irradiation-induced lymphomagenesis while inhibition of BNIP3 or NIX promotes tumor progression." (PMID 25810907, 2015).
tumor (continued). "This work also reported that BNIP3 repressed Rheb activity resulting in reduced mTOR activity and slower cell growth, consistent with a tumor suppressor function for BNIP3." (PMID 25810907, 2015). "The identity of Bnip3 as a positive prognostic indicator of tumor progression appears paradoxical with its role as a pro-apoptotic mediator, and some have concluded that Bnip3 can actually provide a survival function by increasing reparative autophagy." (PMID 24811485, 2014). "We believe that our results warrant further studies on combination therapy focused on maximal Bnip3 activation in the hypoxic zone, and blockade of compensatory pathways by which the tumor cells evade such death." (PMID 24811485, 2014). "BNIP3 was detected in 38 of 50 tumors (76%) and 21 of 50 normal tissues (42%) and was higher in tumor compared to normal tissue (p = 0.004)." (PMID 24551593, 2014). "Many tumor cells have evolved pathways to evade Bnip3-mediated death attesting to the physiological relevance of the survival threat imposed by Bnip3." (PMID 24811485, 2014). "SIM2s expression, concomitant with its repression of BNIP3, enhances tumor cell survival under prolonged hypoxic conditions." (PMID 25197670, 2014). "Shorter disease-free survival (DFS) was associated with Glut-1 positivity (P = 0.010), BNIP3 negativity, tumor phenotype (HER2 and TNBC; P < 0.001) and tumor metabolic type (reverse Warburg type; P = 0.037)." (PMID 24020991, 2013). "Levels of NIX and BNIP3 mRNA were higher in the tumor samples compared to the normal samples in 5/5 and 3/5 cases, respectively." (PMID 22984526, 2012). "Another study using an experimental mouse model showed that expression of BNIP3 protein was inversely correlated with the ability of tumor cells to metastasize." (PMID 19505343, 2009). "Hypoxia-induced autophagy via BNIP3 has been claimed to be a survival mechanism promoting tumor progression." (PMID 19505343, 2009). "We initially used RT–PCR to evaluate BNIP3 expression in a panel of 20 haematopoietic tumour cell lines." (PMID 15756280, 2005). "Notably, traditional Chinese medicine YiFeiSanjieWan mitigates CRF symptoms by inhibiting the Stat3/HIF-1α/BNIP3 signaling pathway, which is induced by aberrantly activated tumor-related inflammation." (PMID 41018226, 2025). "In addition, UALCAN TCGA project analysis revealed that higher BNIP3 expression in HNSC primary tumour samples correlated with decreased patient survival." (PMID 39945227, 2025). "Although BNIP3- or NIX-induced mitophagy is associated with hypoxia, it is known that ataxin-3 can induce hypoxia in tumor cells; thus, hypoxia-mediated mitophagy may be relevant in SCA3/MJD." (PMID 39941093, 2025). "In OS, recent studies suggest that BNIP3 may contribute to tumor aggressiveness by promoting a hypoxia-tolerant TME, thus representing a potential target for therapeutic intervention." (PMID 40860619, 2025). "Furthermore, tumour‐derived PCS combined with Cdh1 to enhance Bnip3‐dependent mitophagy activity of Tim4 positive tumour‐associated macrophages (TAMs)." (PMID 40604335, 2025). "The expression of BNIP3 in primary tumour tissues was significantly higher than in normal tissues." (PMID 39945227, 2025). "Importantly, further KO of Bnip3 and Hif1α/2α abrogated tumor growth delay observed in Vhl-KO MC38 tumors." (PMID 39050705, 2024). "Of note, BNIP3 inhibition significantly sensitized the anti-tumor efficacy of lenvatinib in HCC." (PMID 38969639, 2024). "Moreover, HIF-1α augments autophagy by modulating the expression of BNIP3, a protein central to stress adaptation mechanisms that fortify tumor cell survival while sidestepping apoptosis." (PMID 38240686, 2024).
tumor (continued). "In the absence of external estrogen administration, overexpression of BNIP3 in ER-positive cells (MCF-7 cells) enhanced their tumorigenic potential in a mouse xenograft model, and there was a positive correlation between tumor size and BNIP3 expression intensity." (PMID 39472438, 2024). "In addition, we evaluated the effect of BNIP3 on cell competition through treating the cell competition xenograft models in vivo with BNIP3 inhibitor olomoucine and found that the specific inhibition of BNIP3 effectively suppressed tumor growth." (PMID 38969639, 2024). "FTO regulates BNIP3 to influence tumor growth and metastasis in breast cancer." (PMID 39363112, 2024). "Given the role of senescence in tumor suppression and doxorubicin cardiotoxicity, the reported phenotypes of BNIP3 knockout mice may be due to impaired senescence induction." (PMID 39454000, 2024). "Interestingly, the ablation of Parkin-independent mitophagy receptors BNIP3 or BNIP3L/NIX exhibits the opposite roles for tumor progression in different spontaneous mouse cancer models." (PMID 38067169, 2023). "In this study, we demonstrated that the tumor inflammatory microenvironment leads to the abnormal activation of the Stat/HIF-1α/BNIP3 signaling pathway in skeletal muscle cells, which induces excessive mitophagy in skeletal muscle and ultimately leads to fatigue." (PMID 36814560, 2023). "YFSJ can reduce the level of inflammation in the tumor microenvironment in vivo, inhibit the abnormal activation of the Stat3/HIF-1α/BNIP3 signaling pathway induced by tumor-related inflammation, thereby inhibiting the overactivation of mitophagy in skeletal muscle, and finally alleviate CRF." (PMID 36814560, 2023). "Knockout of BNIP3 disrupts mitochondrial function and induces tumor progression." (PMID 36831455, 2023). "This, in turn, acts as a tumor-suppressive factor by regulating the expression of BNIP3 and NIX." (PMID 38067169, 2023). "In addition, pan-cancer analysis revealed that BNIP3 was also differentially expressed in different tumor tissues compared to that in normal tissues, including LAML, COAD, and KIRC, which was consistent with previous studies." (PMID 37190333, 2023). "BNIP3 and BNIP3L are two BH3 domain-only proteins that have been reported to be associated with cell apoptosis, mitochondrial dysfunction, and mitophagy, and many previous studies have indicated that they are tumour suppressor genes." (PMID 37005657, 2023). "Interestingly, some studies have shown that BNIP3 expression is upregulated in activated NK cells and is involved in promoting NK cell-mediated cytotoxicity against tumor cells." (PMID 37509299, 2023). "Interestingly, elevations in Bnip3 mRNA content as a result of LLC tumor seemed to be attenuated with Pgc1α overexpression in TA muscle in male, and a similar pattern was noted with female mice and Beclin mRNA content in both plantaris and TA in male mice." (PMID 35700525, 2022). "Tumor cells are sensitive to cisplatin and gemcitabine when BNIP3 upregulates." (PMID 36092153, 2022). "Hypoxia-induced autophagy through BNIP3 has been validated to accelerate tumor progression." (PMID 35200106, 2022). "Additionally, Niu and colleagues reported that FTO exerted its pro-tumor activity by downregulating the expression of Bcl-2 nineteen kilodalton interacting protein 3 (BNIP3), a pro-apoptotic member of the Bcl-2 family of apoptotic proteins." (PMID 35628623, 2022). "Nuclear BNIP3 in invasive breast cancer was associated with smaller tumour size, lower tumour grade, and ER positivity, but not with survival." (PMID 36200262, 2022). "By contrary, silencing of BNIP3 showed tumor-suppressing properties in BC." (PMID 35200106, 2022). "For example, in glioblastoma cells, although the BNIP3 expression level was increased in the hypoxic region of the tumour, it was not localized in the mitochondria or cytoplasm, but in the nucleus, and its nuclear localization was a sign of tumour dormancy." (PMID 36200262, 2022).
tumor (continued). "This also reaffirms the key role of BNIP3 as a tumour suppressor." (PMID 36200262, 2022). "Contradictorily, there exists evidence suggesting the tumor-suppressing function of BNIP3." (PMID 35200106, 2022). "In addition, we showed that treatment with TMZ (100 mg·kg−1·d−1, ip) for 12 days in C6 cell xenograft mice markedly inhibited tumor growth accompanied by inducing FOXO3a upregulation, oxidative stress and BNIP3-mediated mitophagy in tumor tissues." (PMID 33879840, 2021). "Although knockdown of BNIP3 alone or radiation treatment could inhibit tumor growth compared with control groups (p < 0.05), the combined effect of BNIP3 and radiation significantly reduced the tumor growth (p < 0.001)." (PMID 33795637, 2021). "On the other hand, BNIP3 has been reported to induce autophagy in tumor cells." (PMID 33795637, 2021). "Further, IHC staining of the tumor xenograft tissue showed that knockdown of BNIP3 could effectively reduce the expression of LC3II, although radiation could promote the expression of LC3 to a certain extent." (PMID 33795637, 2021). "Another potential survival pathway regulated by HIF1α in tumor cells is through the increased expression of BCL2/adenovirus E1B 19 kDa protein-interacting protein 3 (BNIP3), a component of autophagosomes that complexes with p62 LC3 complex proteins to initiate a survival mechanism of self-renewal." (PMID 34396954, 2021). "Mice lacking Bnip3 display more rapid tumor growth than wild‐type mice, which can be caused by excess accumulation of dysfunctional mitochondria and elevated ROS production." (PMID 33438778, 2021). "This dichotomic effect of BNIP3 as a tumor-suppressor or an oncogene may be explained by alternative splicing of BNIP3 generating different isoforms of the receptor with opposite effects." (PMID 34282749, 2021). "However, studies have shown that both tumor cells and cardiac myocytes can utilize the BNIP3 pathway under stress." (PMID 32960902, 2020). "Besides apoptosis, BNIP3 plays a crucial role in autophagy, metabolic pathways, and metastasis-related processes in different tumor types." (PMID 33207677, 2020). "Furthermore, enhanced expression of BNIP3 is usually correlated with the aggressive tumor phenotype and a poor prognosis." (PMID 33207677, 2020). "Under hypoxia conditions, HIF-1 induces up-regulation of Nix and BNIP3 expression in tumor tissues." (PMID 32587855, 2020). "Differential expression of BNIP3 was observed across different tumor stages and M stages." (PMID 31938577, 2020). "The inhibition of BNIP3 by Rheb under the interaction of Rheb and BNIP3 decreases the activity of mTOR signal, and suppresses cell growth, which corresponds to the role of BNIP3 in tumor inhibition." (PMID 32587855, 2020). "Interestingly, BNIP3 expression has been reported to increase in the early stages of breast cancer but it is suppressed as tumours become hypoxic." (PMID 31936236, 2020). "However, similarly to PINK1/PARKIN, BNIP3 can not only serve as a tumor suppressor, but can also exert oncogenic activity." (PMID 32587855, 2020). "The development of chemical agents for BNIP3 targeting could be a prospective strategy to overcome radioresistance acquired during inoperable tumor therapy." (PMID 33207677, 2020). "BNIP3 dramatically alleviated FTO-dependent tumor growth retardation and metastasis." (PMID 30922314, 2019). "Similarly, CA-IX, VEGF and BNIP3 levels were elevated in tumor compared to normal tissue, (p < 0.001, p < 0.001, p < 0.001 respectively, paired t-test)." (PMID 30943919, 2019). "We found that silencing BNIP3 could significantly alleviate FTO-dependent tumor growth retardation in vitro and in vivo." (PMID 30922314, 2019). "In addition, HIF1A promotes autophagy by altering the expression of BCL2/adenovirus E1B 19 kDa protein-interacting protein 3 (BNIP3), which is part of a stress adaptation mechanism that promotes tumor cell survival and avoids cell death." (PMID 31744467, 2019).
tumor (continued). "All the results show that miR-24-3p-BNIP3- mitophagy is related with xenografted tumor growth." (PMID 29632473, 2018). "BNIP3 is also known as a hypoxia-responsive protein, leading to autophagy, which may promote both tumor suppression and tumor growth." (PMID 29888265, 2018). "Mouse models also support a tumor suppressive role for BNIP3, since BNIP3 KO promotes tumor growth." (PMID 29971063, 2018). "BNIP3 overexpression could directly enhance the synergistic anti-tumor effects of EMAP-II and TMZ by inducing mitophagy." (PMID 29632473, 2018). "In addition, BNIP3 was shown to be upregulated in such malignant tumours via HIF-α-mediated signalling in a hypoxic microenvironment." (PMID 28195146, 2017). "The downregulation of BNIP3 under hypoxic conditions may provide an advantage towards the increased survival of the tumor cells, whereas patients with low BNIP3 levels are expected to exhibit lower survival rate." (PMID 28968982, 2017). "Both Bnip3 and Nix translation is increased in hypoxic and peri-necrotic tumor regions." (PMID 26611876, 2016). "Therefore, inhibition of autophagic cell death by BNIP3 repression enhances tumor cell survival under prolonged hypoxic conditions." (PMID 25197670, 2014). "VEGF and BNIP3 protein levels were also inversely correlated to tumor ascorbate content." (PMID 24551593, 2014). "HIF-1α, VEGF, and BNIP3 were elevated in tumor samples (p < 0.01)." (PMID 24551593, 2014). "Tumoral BNIP3 and stromal BNIP3 were highest in the AR-positive and HER-2-negative group." (PMID 25140630, 2014). "This may be relevant to GBM tumor cell survival because BNIP3 is primarily localized in the nucleus in the majority of GBM tumors and correlates with lower levels of DR5 expression." (PMID 23579274, 2013). "(aka NIX); BCL2/adenovirus E1B 19 kd-interacting protein (BNIP)gene that may function simultaneously with BNIP3 and play arole in tumor suppression." (PMID 22546513, 2012). "BNIP3 protein expression was often nuclear in normal breast, but cytoplasmic in tumor cells." (PMID 19505343, 2009). "Knockdown of BNIP3 increased tumor size and induced metastases." (PMID 19505343, 2009). "Similarly, exclusively stromal (and not epithelial) expression of CA9 was an indicator of a poorer prognosis in both BNIP3 methylated and unmethylated tumours (P=0.0495 and P=0.0725, respectively)." (PMID 18728663, 2008). "Conceivably, the lower apoptotic activity in tumours with functional BNIP3 might be due to autophagic rescue of the tumour cells." (PMID 18728663, 2008). "Future clinicopathological analysis may clarify whether there is a specific phenotype for tumours with BNIP3 methylation." (PMID 15756280, 2005). "Moreover, tumor cells may evade immune recognition by upregulating mitophagy receptors such as BNIP3 and FUNDC1, leading to a state of immune tolerance." (PMID 41551160, 2025). "Furthermore, BNIP3 was similarly expressed at higher levels in tumor tissues." (PMID 39050705, 2024). "This suggests that BNIP3 may contribute to the anti-tumor immune response mediated by NK cells." (PMID 37509299, 2023). "However, globally, it was not difficult to find that BNIP3 expression was dysregulated in many cancers, and whether BNIP3 acts as a tumour suppressor or a tumour promoter depends on the cancer context." (PMID 36200262, 2022). "Interestingly, BNIP3 is a pro-apoptotic protein that promotes tumor cell apoptosis." (PMID 36675706, 2022). "Concerning the radiobiological effects, it has been found that I-125 could inhibit cell proliferation in vitro and delay tumor growth in tumor models by upregulating apoptosis- and cell arrest-related genes, such as BNIP3 and WNT9A, through irradiation-induced DNA methylation." (PMID 34660280, 2021).